RNASEK (ribonuclease K)
Description:
Endoribonuclease which preferentially cleaves ApU and ApG phosphodiester bonds. Hydrolyzes UpU bonds at a lower rate. Regulates the activity of vacuolar (H+)-ATPase (V-ATPase) which is responsible for acidifying and maintaining the pH of intracellular compartments. Required at an early stage of receptor-mediated endocytosis. (Microbial infection) Required at an early stage of both clathrin-mediated and clathrin-independent endocytic uptake of a diverse set of viruses, including dengue, West Nile, Sindbis, Rift Valley Fever, influenza, and human rhinoviruses.
Synonyms: MGC71993
Tractability: Small molecule: a structure with a bound ligand is known. Antibody: UniProt predicts a signal peptide or a membrane-spanning region. PROTAC: ubiquitination databases record sites on it.
Gene: Protein-coding gene on chromosome 17 (7,012,417 to 7,014,532, forward strand). Ensembl gene ENSG00000219200.
Subcellular location: Endomembrane system; Cytoplasmic vesicle, clathrin-coated vesicle membrane
Pathways (Reactome):
Disease: Dengue Virus Attachment and Entry
Gene Ontology:
Molecular function: protein binding; RNA endonuclease activity
Biological process: endosomal lumen acidification; proton transmembrane transport; receptor-mediated endocytosis; receptor-mediated endocytosis of virus by host cell; Golgi lumen acidification; intracellular pH reduction; lysosomal lumen acidification; vacuolar acidification
Cellular component: endomembrane system; membrane; endosome membrane; Golgi membrane; lysosomal membrane; plasma membrane; proton-transporting V-type ATPase complex; vacuolar proton-transporting V-type ATPase, V0 domain; clathrin-coated vesicle membrane
Genetic constraint (gnomAD): Loss-of-function variants: 6 observed, 9.91 expected, observed/expected ratio (o/e) 0.61, 90% interval 0.33 to 1.19. That is too few expected variants to judge how well the gene tolerates losing a copy. Missense variants: 101 observed, 128.7 expected, observed/expected ratio (o/e) 0.78, 90% interval 0.67 to 0.93. Synonymous variants: 46 observed, 50.75 expected, observed/expected ratio (o/e) 0.91, 90% interval 0.71 to 1.16.
Homologues: Orthologues: chimpanzee RNASEK (100% identical), mouse Rnasek (100% identical), rat Rnasek (100% identical), pig RNASEK (98% identical), guinea pig RNASEK (96% identical), tropical clawed frog rnasek (82% identical), rabbit RNASEK (74% identical), zebrafish rnasekb (73% identical), zebrafish rnaseka (70% identical).
Diseases named in the same sentence as RNASEK in open-access papers:
RNASEK is named in the same sentence as 23 diseases in open-access papers, as found by Europe PMC text mining. Sharing a sentence is not in itself a finding about the gene and the disease. The quoted sentences say what the papers report.
prostate carcinoma (3 papers, 2024 to 2025). A carcinoma that arises from epithelial cells of the prostate gland. "RNASEK is linked to reduced prostate cancer risk, and PPIA acts as an oncogene in various cancers, negatively correlating with immune checkpoints and immune cell infiltration." (PMID 40340807, 2025). "Therefore, we might infer that RNASEK played a significant role in the carcinogenesis of prostate cancer, which aligned with the results of the Manhattan plot exhibition." (PMID 39600951, 2024). "What’s more, our research demonstrated that specific genes, encompassing RNASEK, CPEB2, ARHGAP22, and BRD1, were enriched in the different cell clusters of prostate cancer tissues through the single-cell RNA sequencing localization analysis." (PMID 39600951, 2024).
viral infection (3 papers, 2021 to 2025). "Altogether, RNASEK plays a pivotal role in multiple serious viral infections; hence, detailed molecular mechanism by which RNASEK enhances type I IFN secretion for antiviral response should be elucidated as soon as possible." (PMID 34880860, 2021). "Altogether, RNASEK is essential for cancer progress and viral infections, suggesting that it may be involved in innate immune response." (PMID 34880860, 2021). "The human Ribonuclease K (RNASEK) gene is involved in various cellular processes, such as viral infection, immune response, and maintaining cellular homeostasis." (PMID 40546550, 2025).
Co-infection (2 papers, 2020 to 2025). "Pre-infection and co-infection with cell-fusing agent virus (CFAV) significantly enhance DENV2 replication in Aag2 cells by increasing the expression of ribonuclease kappa." (PMID 40045350, 2025). "Co-infection studies using cell-fusing agent virus (CFAV, Flavivirus) and dengue virus (DENV) in Aag2 cells shows mutual interaction through activation of Ribonuclease K (AeRNASEK) expression, whereas in Ae. aegypti mosquitoes, CFAV negatively interfered with DENV-1 and ZIKV infection." (PMID 32295109, 2020).
osteosarcoma (2 papers, 2017 to 2024). A usually aggressive malignant bone-forming mesenchymal neoplasm, predominantly affecting adolescents and young adults. "Knockout of RNAseK in the human osteosarcoma cells, U2OS, also resulted in LC3-II accumulation and disrupted degradation." (PMID 39231962, 2024). "The role of RNASEK in replication of these viruses was examined in Drosophila S2 cells and human osteosarcoma cells (U2OS) but not in mosquito cells." (PMID 28761113, 2017).
ovarian carcinoma (2 papers, 2021 to 2025). A malignant neoplasm originating from the surface ovarian epithelium. "On the other hand, in late-stage ovarian cancer, increased expression of RNASEK has been associated with resistance to chemotherapy and worse survival rates." (PMID 40546550, 2025). "Paclitaxel, an anti-cancer drug, induces the apoptosis of BT-20 breast and SKOV-3 ovarian cancer cells, accompanying the elevated expression of RNASEK (up to 9-fold)." (PMID 34880860, 2021).
acute myeloid leukemia (1 paper, 2025). Acute myeloid leukemia (AML) is a group of neoplasms arising from precursor cells committed to the myeloid cell-line differentiation. "We found that high expression of RNASEK was associated with good prognosis in PAAD patients (hazard ratio (HR): 0.49, P = 0.0007) and acute myeloid leukemia (LAML) patients (HR: 0.53, P = 0.029)." (PMID 40546550, 2025).
cholangiocarcinoma (1 paper, 2025). A carcinoma that arises from the intrahepatic biliary tree (intrahepatic cholangiocarcinoma) or from the junction, or adjacent to the junction, of the right and left hepatic ducts (hilar cholangiocarcinoma). "The results from the GEPIA database revealed that RNASEK was significantly upregulated (P < 0.05) in cholangiocarcinoma (CHOL) and pancreatic adenocarcinoma (PAAD)." (PMID 40546550, 2025).
endometrial cancer (1 paper, 2025). Primary or metastatic malignant neoplasm involving the endometrium (mucous membrane that lines the endometrial cavity). "Furthermore, our genomic analysis identified frequent genetic alterations in RNASEK particularly deep deletions in miscellaneous neuroepithelial tumors, amplifications in SARC, and finally mutations in endometrial cancers." (PMID 40546550, 2025). "RNASEK alterations were rare across tumor types; they exhibited deep deletions in miscellaneous neuroepithelial tumors, amplification in SARC, and mutations were identified in endometrial cancer." (PMID 40546550, 2025).
pancreatic adenocarcinoma (1 paper, 2025). "Moreover, High RNASEK expression indicated a good prognosis in pancreatic adenocarcinoma (PAAD) (hazard ratio (HR) 0.49, P = 0.0007)." (PMID 40546550, 2025).
thyroid cancer (1 paper, 2025). "This contrasting pattern suggests a complex and potentially unique role for RNASEK in the immune landscape of thyroid cancer." (PMID 40546550, 2025).
uterine corpus endometrial carcinoma (1 paper, 2025). A endometrial carcinoma (disease) that involves the body of uterus. "This was accompanied by notable hypomethylation in BLCA, HNSC, LIHC, and Uterine Corpus Endometrial Carcinoma (UCEC), associated with increased RNASEK expression." (PMID 40546550, 2025).
infection (4 papers, 2017 to 2025). The state of being infected such as from the introduction of a foreign agent such as serum, vaccine, antigenic substance or organism. "Ribonuclease kappa (RNASEK), is known to promote infection of acid-dependent viruses that rely on endocytosis and pH-dependent entry, including DENV." (PMID 35006065, 2022). "To confirm that RNASEK promotes DENV replication in mosquito cells, we silenced RNASEK in Aa20 cells by transfection of dsRNASEK into the cells followed by their infection with 1 MOI of DENV-2." (PMID 28761113, 2017). "Ribonuclease kappa (RNASEK) was shown to promote infection of a range of viruses that rely on endocytosis and pH-dependent entry, including DENV16." (PMID 28761113, 2017). "We have shown that CFAV infection leads to increase in the expression of ribonuclease kappa (RNASEK), which is known to promote infection of viruses that rely on endocytosis and pH-dependent entry." (PMID 28761113, 2017).
cancer (3 papers, 2021 to 2025). A tumor composed of atypical neoplastic, often pleomorphic cells that invade other tissues. "This study investigated how RNASEK functions as a diagnostic and prognostic biomarker in a human pan-cancer dataset." (PMID 40546550, 2025). "Identifying eight novel alternatively spliced RNASEK variants with widespread expression in human cancer cell lines further emphasizes its biological significance in cancer development." (PMID 40546550, 2025). "Further investigation is required to elucidate the specific mechanisms underlying RNASEK's prognostic value in these cancers." (PMID 40546550, 2025). "This makes RNASEK a potential diagnostic and/or prognostic biomarker in various types of cancers." (PMID 40546550, 2025). "However, further investigation into the mechanisms underlying the role of RNASEK in cancer biology as a diagnostic or therapeutic intervention." (PMID 40546550, 2025). "In conclusion, this study’s pan-cancer analysis revealed that RNASEK could be a potential diagnostic biomarker in six types of cancers, including BLCA, CHOL, ESCA, HNSC, LIHC, and THCA." (PMID 40546550, 2025). "Hence, given that the pro-apoptosis effects of RNASEK are associated with various cancers or other immune-related diseases, clarifying the mechanism by which RNASEK exerts its function is much necessary." (PMID 34880860, 2021). "These varied racial patterns in RNASEK expression demonstrate the complex interaction between genetic predisposition, environmental factors, and cancer development, emphasizing the importance of considering racial differences in cancer research and treatment strategies." (PMID 40546550, 2025). "Our study showed marked RNASEK expression variations across cancer stages in ESCA, HNSC, LIHC, and THCA patients." (PMID 40546550, 2025). "RNASEK was significantly upregulated in seven types of cancer (P < 0.05), including BLCA, CHOL, ESCA, HNSC, LIHC, KICH, and THCA." (PMID 40546550, 2025). "In CHOL, significant differences were only observed between normal and Caucasian groups, suggesting possible genetic or environmental factors specific to Caucasian populations that influence RNASEK expression in this cancer type." (PMID 40546550, 2025). "Our study provides valuable insights into the role of RNASEK across different cancers using publicly available databases." (PMID 40546550, 2025). "In various types of cancer, the mRNA expression of RNASEK showed notable prognostic connections in pan-cancer patients." (PMID 40546550, 2025). "The differing observations indicate that the involvement of RNASEK in cancer is intricate and reliant on context, varying based on cancer type and stage of progression." (PMID 40546550, 2025). "Our study found that RNASEK expression is elevated in several cancer types (BLCA, HNSC, LIHC, UCEC) due to reduced DNA methylation." (PMID 40546550, 2025). "First, all the analyses were based on bioinformatics tools, further experiments to clarify the precise mechanisms by which RNASEK contributes to cancer development and progression are needed in the future." (PMID 40546550, 2025). "We studied RNASEK expression concerning pathological and clinical features, including stage, race, and age, in six types of cancers (BLCA, CHOL, ESCA, HNSC, LIHC, and THCA) via the UALCAN database." (PMID 40546550, 2025). "By cross-referencing the results confirmed by two databases, TIMER and UALCAN, we concluded that RNASEK was commonly upregulated in six types of cancers, including BLCA, CHOL, ESCA, HNSC, LIHC, and THCA." (PMID 40546550, 2025). "Our analysis of RNASEK expression across cancer stages revealed significant differences between stage 1 compared to stage 3 in ESCA, HNSC, and THCA, and significant differences were observed between stages 2 and 3 when compared to stage 4 in LIHC patients." (PMID 40546550, 2025). "Our study provides novel insights into the potential role of RNASEK in cancer immunity." (PMID 40546550, 2025).
cancer (continued). "Furthermore, the importance of RNASEK in cancer is supported by the general role of ribonucleases in RNA degradation, which influences critical cellular processes including growth, apoptosis, and angiogenesis." (PMID 40546550, 2025). "However, the specific role of human RNASEK in cancer progression remains poorly understood, and further investigations are needed." (PMID 40546550, 2025). "However, the impact of RNASEK on survival varied across different cancers, suggesting its complex role in tumorigenesis." (PMID 40546550, 2025). "Moreover, the expression of the RNASEK gene and its potential implications in various types of cancer have been explored." (PMID 40546550, 2025). "This study investigated RNASEK as a potential pan-cancer biomarker." (PMID 40546550, 2025). "RNASEK is expressed as one main transcript in nearly all human tissues and developmental stages, as well as in many carcinomas, which may explain its involvement in the carcinogenesis process." (PMID 40546550, 2025). "RNASEK, found in metazoans, contributes to tumor development, but the lack of systemic pan-cancer investigation into the diagnostic and prognostic function of RNASEK, epigenetic regulation, and interaction with the immune cell infiltration remains unclear." (PMID 40546550, 2025). "However, despite the progress made in considering the role of RNASEK in human cancers, the possible participation remains unclear and needs to be further elucidated." (PMID 40546550, 2025). "Conversely, the six downregulated genes (SERPINE1, TNFRSF12A, PHLDA1, RNASEK, PPIA, and G0S2) are involved in diverse cancer-related pathways." (PMID 40340807, 2025). "We investigated the correlation between RNASEK expression and immune cells (B cells, CD8+ T-cells, CD4+ T-cells, macrophages, neutrophils, and dendritic cells) in six cancers, including BLCA, CHOL, ESCA, HNSC, LIHC, and THCA." (PMID 40546550, 2025). "Moreover, the RNASEK gene is transcribed via expressed sequence tag (EST) analysis in the vast majority of normal and cancerous human tissues; 75% of these sequences are present in cancer tissues, and 25% of them are present in normal tissues." (PMID 40546550, 2025). "This broad age range of RNASEK upregulation suggests that its role in these cancers may not be strictly age-dependent." (PMID 40546550, 2025).
tumor (2 papers, 2021 to 2025). "This relationship suggests that RNASEK may play a role in macrophage recruitment or survival within the tumor microenvironment." (PMID 40546550, 2025). "This association with multiple immune cell types suggests that in LIHC, RNASEK might be involved in tumor progression." (PMID 40546550, 2025).
RNASEK also shares sentences with these, for which no sentence is quoted: brain tumors (1 paper); cervical squamous cell carcinoma (1); glioma (1); lung adenocarcinoma (1); melanoma (1); neuroepithelial tumors (1); Pancreatic Cancer (1); sarcoma (1); ZIKV infection (1).